IL33 (interleukin 33)
Diseases named in the same sentence as IL33 in open-access papers (continued):
Sharing a sentence is not in itself a finding about the gene and the disease.
prediabetes (continued). "We initially asked whether the level of adipose tissue IL-33 (and/or ST2) was differentially expressed among individuals with normoglycemia, prediabetes, or T2D." (PMID 31073344, 2019). "Comparative analysis confirmed that higher levels of IL-33 were associated with significantly lower CCL7 in individuals with normoglycemia (P = 0.02; median 16.7, n = 10 vs. median 118.8, n = 9) but not in those with prediabetes or T2D." (PMID 31073344, 2019). "Thus, there appears to be an important dynamic between IL-33 and ST2 in the adipose tissue; one that influences overall glycemia and may be dysfunctional in individuals with prediabetes." (PMID 31073344, 2019). "Interestingly, however, IL-33 was directly associated with FGL2 in individuals with normoglycemia and T2D but not in those with prediabetes." (PMID 31073344, 2019). "IL-33 was inversely correlated with HbA1c in individuals with normoglycemia (r = −0.6; P = 0.004; n = 20) and T2D (r = −0.3; P = 0.036; n = 47) but not in those with prediabetes." (PMID 31073344, 2019). "Furthermore, IL-33 was directly correlated with IL-12A (IL-12B was not tested) in individuals with T2D (r = 0.42; P = 0.007; n = 41) but not in those with normoglycemia or prediabetes." (PMID 31073344, 2019). "Taken together, our results suggested that adipose tissue IL-33 was inversely associated with overall glycemia but directly associated with ST2 and, importantly, that these patterns of associations were only observed in individuals with normoglycemia and T2D but not in those with prediabetes." (PMID 31073344, 2019). "However, it is not known whether metabolic effects of adipose tissue IL-33 differ among individuals with normoglycemia, prediabetes, and T2D." (PMID 31073344, 2019). "Only diabetic patients demonstrated positive correlation between sST2 and IL-33 (r = 0.44, P = 0.05), although such correlation was not evident in the entire cohort or in individuals with NGT or prediabetes." (PMID 32101157, 2020). "The ratio of IL-33 to ST2 was inversely correlated with HbA1c in individuals with normoglycemia (r = −0.7; P = 0.001; n = 17) but not in those with prediabetes or T2D." (PMID 31073344, 2019). "Similarly, higher levels of IL-33 were associated with significantly higher PRDM16 in individuals with normoglycemia (P = 0.03; median 7.9, n = 10 vs. median 3.3, n = 10) and T2D (P = 0.02; median 6.1, n = 25 vs. median 4.1, n = 18) but not in those with prediabetes." (PMID 31073344, 2019). "Similarly, higher levels of IL-33 were associated with significantly higher ST2 in individuals with normoglycemia (P = 0.004; median 2.45, n = 8 vs. median 1.69, n = 10) and T2D (P = 0.005; median 2.83, n = 27 vs. median 1.83, n = 16) but not in those with prediabetes." (PMID 31073344, 2019). "IL-33 was directly correlated with ST2 in individuals with normoglycemia (r = 0.63; P = 0.005; n = 18) and T2D (r = 0.54; P = 0.0002; n = 43) but not in those with prediabetes." (PMID 31073344, 2019). "With regard to PRRs, IL-33 was directly correlated with the C-type lectin receptor CD302 in individuals with normoglycemia (r = 0.54; P = 0.01; n = 21) and T2D (r = 0.41; P = 0.004; n = 47) but not in those with prediabetes." (PMID 31073344, 2019). "However, IL-33 was inversely correlated with CCL7 in individuals with normoglycemia (r = −0.5; P = 0.02; n = 19) but not in those with prediabetes or T2D." (PMID 31073344, 2019). "Although IL-33 was not correlated with UCP1 or COX7A1, it was directly correlated with PR domain containing 16 (PRDM16) in individuals with normoglycemia (r = 0.5; P = 0.02; n = 20) and T2D (r = 0.38; P = 0.01; n = 43) but not in those with prediabetes." (PMID 31073344, 2019). "Similarly, IL-33 was inversely correlated with CCL8 in individuals with normoglycemia (r = −0.48; P = 0.04; n = 18) but not in those with prediabetes or T2D." (PMID 31073344, 2019).
prediabetes (continued). "However, IL-33 was directly correlated with fibrinogen-like protein 2 (FGL2) in individuals with normoglycemia (r = 0.48; P = 0.03; n = 21) and T2D (r = 0.3; P = 0.04; n = 47) but not in those with prediabetes." (PMID 31073344, 2019).
prion disease (3 papers, 2021 to 2025). A transmissible disease that is caused by a protein that is able to induce abnormal folding of normal cellular proteins, leading to characteristic spongiform brain changes, which are associated with neuronal loss without an inflammatory response. "Reactive astrocytes including those associated with prion diseases upregulate expression of IL-33 and C3, which are known to drive microglia-mediated synapse engulfment and elimination." (PMID 34359897, 2021). "As synapse related transcripts were dysregulated here, we speculate that Il33 signaling may serve as a potential link between the dysfunction of neurons and astrocytes in prion disease." (PMID 35651626, 2022).
salivary gland tumors (3 papers, 2018 to 2025). "On the other hand, in malignant salivary gland tumors, nuclear IL-33 expression was limited to epithelial-myoepithelial, acinic, and oncolytic carcinomas." (PMID 30205617, 2018). "Under these circumstances, IL-33 was deemed as a novel prognostic marker for malignant salivary gland tumors with potential use in clinical diagnostics." (PMID 30205617, 2018). "Based on current data, IL-33 may have potential as a biomarker for the diagnosis of salivary gland tumors." (PMID 40807046, 2025). "In patients with salivary gland tumors (WT and PA), various chemokines have been determined, including CCL28, CXCL10, CXCL12, CCL18, and CXCL1, as well as pro-inflammatory cytokines such as IL-1β, IL-6, IL-4, IL-17, and IL-33." (PMID 40807046, 2025). "Poorly differentiated malignant salivary gland tumors that were devoid of myoepithelial cells, such as salivary duct carcinoma, did not express IL-33 which was indicative of poor prognosis." (PMID 30205617, 2018).
sarcoidosis (3 papers, 2017 to 2019). Sarcoidosis is a multisystemic disorder of unknown cause characterized by the formation of immune granulomas in involved organs. "IL-33 was slightly decreased in HP and sarcoidosis compared with NCs (0.17 (0.31–1.73 pg/μg), 0.4 (0.06–1.6 pg/μg) vs. 1.15 (0.63–2.66 pg/μg); p = 0.006 and p = 0.048, respectively)." (PMID 28202030, 2017). "IL-33 was detected in 36 of 40 NCs, 96 of 100 patients with IPF, 20 of 22 patients with NSIP, 14 of 20 patients with HP, and 15 of 19 patients with sarcoidosis." (PMID 28202030, 2017). "The TSLP and IL-33 levels were significantly higher in patients with IPF relative to the NCs (p = 0.01 and p = 0.0001, respectively), NSIP (p = 4.95E − 7 and p = 0.0002, respectively), HP (p = 0.00003 and p = 0.000005, respectively), and sarcoidosis groups (p = 0.003 and p = 0.0001, respectively)." (PMID 28202030, 2017).
sarcoma (3 papers, 2018 to 2025). A usually aggressive malignant neoplasm of the soft tissue or bone. "By analyzing sarcoma data from The Cancer Genome Atlas, we found that higher transcriptional levels of IL-33 and ST2 were associated with a favorable outcome." (PMID 29896199, 2018). "Integrated analysis of TCGA and GEO sarcoma datasets implicated the possible role of the IL-33/ST2 axis in STS." (PMID 29896199, 2018). "Furthermore, we analyzed transcriptome sequencing and survival data from sarcoma from the TCGA and found that both IL-33 and ST2 expression were associated with the prognosis of sarcomas." (PMID 29896199, 2018). "To evaluate the expression of IL-33 and ST2 in STS, we examined 18 pairs of sarcoma and adjacent normal tissue specimens for IL-33 and ST2 expression using real-time PCR assays." (PMID 29896199, 2018). "Furthermore, we found that both IL-33 and ST2 expression were associated with the prognosis of sarcomas; patients with higher transcriptional levels of IL-33 and ST2 have a more favorable prognosis." (PMID 29896199, 2018). "In the public HITS-CLIP dataset (GSE43308), fused in sarcoma (FUS) was identified as an RBP that binds to both MIR205HG and IL33 mRNA." (PMID 40059822, 2025). "Therefore, we analyzed the expression of IL-33/ST2 axis-related genes and clinical survival data of sarcoma from TCGA and GEO, hoping to provide clues as to whether IL-33 can modulate antitumor immunity and reverse the immunosuppressive tumor microenvironment in STS." (PMID 29896199, 2018). "The correlations between the expression of ST2 and CD4, CD8A, and CD33, and between IL-33 and CD8A and CD45RO were then validated by analysis using GSE2719 or GSE 967 GEO datasets of sarcoma." (PMID 29896199, 2018). "T‐cells in the sarcoma microenvironment exhibited elevated levels of cytotoxicity (GZMB, GNLY and KLRD1), exhaustion (HAVCR2, CD38, CD160, CXCL13 and CX3CR1), and inflammation (IL33, PPARG, IL6R and SOCS3), suggesting an activated but exhausted phenotype." (PMID 39658531, 2024). "By analyzing publicly available tumor data from The Cancer Genome Atlas (TCGA), we found that IL-33 and ST2 mRNA is widely expressed in sarcoma, indicating that the IL-33/ST2 axis may play an important role in regulating antitumor immunity in STS." (PMID 29896199, 2018). "The correlations between the IL-33/ST2 axis and CD8+ T cells and IFN-γ, as well as Tregs, MDSCs, and TGF-β1 were validated by additional analyses using three other independent GEO datasets of sarcoma." (PMID 29896199, 2018). "The negative correlations between the expression of IL-33 and CCL20 and TGFB1 were then validated by analysis using GSE6481 or GSE967 datasets of sarcoma." (PMID 29896199, 2018).
scleroderma (3 papers, 2021 to 2023). Scleroderma is a rare autoimmune connective tissue disorder characterized by abnormal hardening of the skin and, sometimes, other organs. "Although there is no clear explanation for the different patterns of IL-33 expression in non-IPF and IPF fibroblasts in our study and that of Luzina and colleagues, it may reflect differences in culture conditions and their inclusion of data from scleroderma patients." (PMID 36949463, 2023).
scrub typhus (3 papers, 2016 to 2026). Scrub typhus is a rare dust mite-borne infectious disease caused by the Orientia tsutsugamushi bacterium and characterized clinically by an eruptive fever which is potentially serious. "This study indicates a pathogenic role of alarmin IL-33 in a murine model of scrub typhus and highlights infection-triggered EC damage and IL-33-mediated pathological changes during the course of Orientia infection." (PMID 26943125, 2016). "On day 4 post-infection, Karp induced significant elevation of transcriptional inflammatory signatures (Ccl2, Il33, Ifng) and inflammatory gene pathways (Il1, Il6, Tnf, Ifng), the characteristics of severe scrub typhus." (PMID 42112365, 2026). "Our observations of reduced induction of IL33 by the less virulent UT176 strain further support a role for this cytokine in the pathogenesis of scrub typhus." (PMID 32620750, 2020). "Regardless of the underlying mechanisms, our data suggest tissue-specific roles of endogenous IL-33 and highlight its contributions in renal injury, cellular apoptosis, and endothelial activation in mouse model of severe scrub typhus." (PMID 26943125, 2016). "To assess the role of IL-33 in scrub typhus progression, we challenged IL-33-/- and WT mice with a lethal dose of Orientia and monitored them daily for disease manifestations." (PMID 26943125, 2016). "To further confirm the role of IL-33 in scrub typhus, we injected rIL-33 to sub-lethally infected mice, and observed the exacerbated illness and increased mortality." (PMID 26943125, 2016). "At present, the role of IL-33 in severe scrub typhus is unclear." (PMID 26943125, 2016). "As expected, our results reveal that IL-33 regulates the balance of Ang1/Ang2 as well as that of eNOS/ET-1, modulating the EC inflammation and tissue dysregulation in the kidneys during severe scrub typhus." (PMID 26943125, 2016). "This is the first study to address the role of IL-33 in a mouse model of scrub typhus." (PMID 26943125, 2016). "However, it is unclear whether IL-33 modulates tissue injury and progression of scrub typhus." (PMID 26943125, 2016).
septic arthritis (3 papers, 2018 to 2021). "In the mouse model of septic arthritis, substantial amounts of IL-33 as well as markedly reduced sST2 levels were observed in the knee joint." (PMID 29867945, 2018). "This suggests that endogenous IL-33 is essential to driving type 2 response in septic arthritis which are mediated by IL-4." (PMID 29867945, 2018). "These clinical and experimental findings are consistent with the notion that the IL-33 levels are tightly regulated by sST2 availability, suggesting that during S. aureus septic arthritis there is an enhanced availability and, potentially, activity of IL-33." (PMID 29867945, 2018). "Thus, the mouse septic arthritis model replicates this IL-33/sST2 balance observed in septic arthritis patients." (PMID 29867945, 2018). "Considering that septic arthritis triggered the production of IL-33 and reduction of sST2 levels in the synovial fluid of patients, we used a model of S. aureus-induced septic arthritis in WT (balb/c) and ST2−/− mice to investigate the disease outcome in the ST2 deficiency scenario." (PMID 29867945, 2018). "Moreover, acute sepsis also presents differences with septic arthritis that contribute to understand the pleiotropic roles of IL-33." (PMID 29867945, 2018). "The intra-articular injection of 1 × 107 colony-forming unity/10 μl of S. aureus American Type Culture Collection 6538 in wild-type (WT) mice induced IL-33 and sST2 production with a profile resembling the observation in the synovial fluid of septic arthritis patients." (PMID 29867945, 2018). "Despite the detection of IL-33 in the synovial fluid and knee joints of septic arthritis patients and mice, respectively, whether IL-33 and its receptor ST2 have a function in disease is unknown." (PMID 29867945, 2018). "As IL-33 and its receptor ST2 have been recognized as an important axis in joint inflammation and infectious diseases, we therefore, investigated whether ST2 deficiency would influence the outcome and contributing mechanisms of this receptor in S. aureus-induced septic arthritis." (PMID 29867945, 2018). "Considering that IL-33 interferes with TLR signaling, it is reasonable to suppose that in ST2−/− mice with septic arthritis, TLR2 signaling will be boosted allowing neutrophils and macrophages to produce larger amounts of NO via iNOS to eliminate the bacteria." (PMID 29867945, 2018). "Thus, to determine the contribution of iNOS to IL-33/ST2 signaling role in septic arthritis, WT and ST2−/−mice with septic arthritis received daily treatment with AMG, a selective iNOS inhibitor." (PMID 29867945, 2018).
skin infection (3 papers, 2014 to 2025). An inflammatory process affecting the skin, caused by bacteria, viruses, parasites, or fungi. "IL-33, as a cytokine from innate immune cells, has been shown to be protective against parasitic and bacterial infection, but the underlying intricate mechanism by which IL-33 is regulated to increase host defenses against bacterial skin infection remains largely unknown." (PMID 24586149, 2014). "Since we have delineated a key mechanism by which S.aureus induces IL-33 in macrophages, we next wanted to establish an in vivo role of IL-33 in S.aureus skin infection." (PMID 24586149, 2014). "Here, we show that S.aureus infection increases IL-33 expression in macrophages, and IL-33 in turn induces and activates iNOS to release NO, thus limiting bacterial growth and/or survival during skin infection." (PMID 24586149, 2014). "Furthermore, to determine which cell type is a major producer of IL-33 during skin infection we used heat-inactivated S.aureus to stimulate primary keratinocytes, mast cells, neutrophils and macrophages in vitro." (PMID 24586149, 2014). "The identification of IL-33 function in the skin provides new insights into pathways contributing to antimicrobial defense and may ultimately lead to the development of novel treatment regimens for skin infection and inflammation." (PMID 24586149, 2014). "IL-33 is an intermediate molecule embedded within the cross-talk between microbes and the host, and may function as a previously unknown key element in the treatment of S.aureus skin infection." (PMID 24586149, 2014).
staphylococcus aureus infection (3 papers, 2014 to 2022). An infectious process in which the bacteria Staphylococcus aureus is present. "In patients with Staphylococcus aureus infection on the skin, IL-33 is markedly increased as compared to the healthy controls and suggested that IL-33 possesses antimicrobial and wound-healing effects." (PMID 27667993, 2016).
subarachnoid hemorrhage (3 papers, 2017 to 2021). A serious neurological disorder characterized by intracranial hemorrhage into the subarachnoid space. "Interleukin-33 (IL-33) was originally discovered in 1999 as clone DVS27 in vasospastic cerebral arteries in a canine model of subarachnoid hemorrhage (SAH)." (PMID 34079543, 2021). "Interleukin-33 (IL-33) was originally discovered (as clone DVS 27) in a study of canine vasospastic cerebral arteries after subarachnoid haemorrhage and received attention due to its highly upregulated expression." (PMID 29180837, 2017). "In a rat model of subarachnoid hemorrhage (SAH), expression of IL-33 in the cerebral cortex after injury is markedly elevated in the SAH together with IL-1β and TNF-a." (PMID 30515150, 2018).
Thrombocytopenia (3 papers, 2012 to 2019). A reduction in the number of circulating thrombocytes. "Furthermore, IL-33 level of patients with SLE was closely correlated with ESR, CRP, and IgA but showed significantly independent association of IL-33 with thrombocytopenia, erythrocytopenia, and anti-SSB antibody." (PMID 24151520, 2013). "Increased IL-33 level was significantly associated with thrombocytopenia, erythrocytopenia, and anti-SSB antibody, suggesting IL-33 may exert biologic effects on erythrocytes and platelets or their precursors in SLE." (PMID 22312407, 2012). "This cytokine pattern (high ST2 level plus normal IL-33) inversely correlated with thrombocytopenia was confirmed in a young DENV-infected population, and it might be the cellular mechanism between sST2 and coagulopathy in DENV infection." (PMID 31877138, 2019).
visceral leishmaniasis (3 papers, 2016 to 2024). A severe form of leishmaniasis characterized by irregular bouts of fever, substantial weight loss, swelling of the spleen and liver, and anemia (which may be serious). "Administering specific inhibitors of nuclear factor of activated T cell 1 and hypoxia-inducible factor 1 alpha in BALB/c mouse model of visceral leishmaniasis decreased liver and spleen parasite burden along with reduction in IL-33 level." (PMID 38750790, 2024). "Host anti-inflammatory responses are critical for the progression of visceral leishmaniasis, and the pleiotropic cytokine interleukin (IL)-33 was found to be upregulated in infection." (PMID 38750790, 2024). "Therefore, in the case of a malnourished patient suffering from an infectious disease such as visceral leishmaniasis, the increased IL-33 might impact on Th1 immune responses, as well as contribute to the inflammation." (PMID 27548305, 2016).